INPPL1 (inositol polyphosphate phosphatase like 1)
Diseases named in the same sentence as INPPL1 in open-access papers:
INPPL1 is named in the same sentence as 69 diseases in open-access papers, as found by Europe PMC text mining. Sharing a sentence is not in itself a finding about the gene and the disease. The quoted sentences say what the papers report.
breast carcinoma (30 papers, 2012 to 2024). "The local consistencies of genes 3636 (INPPL1) and 5027 (P2RX7) were also found to be negatively associated to breast cancer survival." (PMID 31874600, 2019). "Indeed, it has been previously shown that this antibody specifically labels SHIP2 in MCF-7 breast cancer cells but not in the cells deficient for INPPL1 by CRISPR/Cas9 technology and thus was considered as specific for immunostaining." (PMID 38833073, 2024). "Recent studies have described the involvement of phosphatidylinositol 3,4,5-trisphosphate 5-phosphatase 2 (INPPL1) in the migration and metastasis of breast cancer and glioblastoma cells." (PMID 37120454, 2023). "Other studies have demonstrated a positive role of INPPL1 in EGF-induced Akt activation and cell migration in breast cancer cells." (PMID 33546420, 2021). "They discovered a correlation between increased expression of INPPL1 and estrogen receptor negative (ER-negative) primary breast cancer, as well as grade of invasiveness and reduced survival." (PMID 38791291, 2024). "INPPL1 is also known as SHIP2, which is involved in breast cancer development." (PMID 31874600, 2019).
Obesity (16 papers, 2006 to 2025). Accumulation of substantial excess body fat. "SHIP2 has been widely studied in insulin resistance, obesity, and cancer, and recently, it was reported that mutations in INPPL1 cause opsismodysplasia, a rare autosomal recessive severe skeletal dysplasia." (PMID 35832491, 2022). "It has been shown that INPPL1-null mice are highly resistant to dietary obesity." (PMID 17925029, 2007). "For example, Inositol Polyphosphate Phosphatase-Like 1 (Inppl1) knock out mice display insulin hypersensitivity, increased levels of phosphorylated AKT, and protection against diet-induced obesity." (PMID 31262088, 2019). "The product of INPPL1 is the SH2-containing inositol 5'-phosphatase 2 (SHIP2), which is considered an important target in controlling obesity, type 2 diabetes and insulin resistance." (PMID 17925029, 2007). "The position candidate gene INPPL1 has been discovered in Landrace pigs, which has a negative regulatory effect on diet induced obesity and participates in the regulation of insulin function." (PMID 40777826, 2025).
diabetes (13 papers, 2003 to 2024). "Another cross-sectional study with a high number of participants (n = 1074) investigated the INPPL1 gene with respect to a possible correlation with the metabolic syndrome and diabetic nephropathy in Finnish people with diabetes mellitus type 1 (DMT1)." (PMID 38791291, 2024). "A subsequent study in hypertensive subjects without diabetes or metabolic syndrome did not confirm this association suggesting that INPPL1 variants may be specifically involved in mechanisms causing hypertension in insulin-resistant patients." (PMID 23762820, 2013).
type 2 diabetes (13 papers, 2006 to 2025). "The single nucleotide polymorphisms of INPPL1 contribute to the genetic susceptibility to type 2 diabetes and metabolic syndromes." (PMID 38833073, 2024). "For instance, the Inppl1 gene was first identified in the rat as a causative gene of type 2 diabetes and this discovery led to the identification of mutations in the homolog gene of diabetic patients." (PMID 32741357, 2020). "SHIP2, encoded by inositol polyphosphate phosphatase-like 1 (INPPL1), belongs to the phosphoinositide 5-phosphatase family, which has been implicated in some human diseases such as type 2 diabetes, Alzheimer’s disease and Opsismodysplasia." (PMID 32183047, 2020).
opsismodysplasia (9 papers, 2014 to 2023). "SHIP2 is directly implicated in several human diseases: mutations in INPPL1 cause opsismodysplasia, a rare autosomal recessive disease characterized by delayed bone maturation." (PMID 33716646, 2021). "Recent studies have reported that INPPL1 mutations were a cause of Opsismodysplasia, while increased miRNA-205 suppressed SHIP2 expression in squamous cell epithelium." (PMID 28117748, 2017). "Both SOS1 and INPPL1 are associated with growth disorders – Noonan syndrome and opsismodysplasia." (PMID 27651465, 2016). "This couple was also found to be carriers for mutation in the INPPL1 gene, which is responsible for AR opsismodysplasia (OPSMD)." (PMID 37260775, 2023). "Both were found to be carriers for another AR disorder: opsismodysplasia (OPSMD), which is caused by homozygous or compound heterozygous mutation in the INPPL1 gene on chromosome 11q13." (PMID 37260775, 2023). "We present two siblings affected with opsismodysplasia (OPS), a rare skeletal dysplasia caused by mutations in the inositol polyphosphate phosphatase-like 1 gene." (PMID 26157786, 2015).
Alzheimer disease (8 papers, 2016 to 2024). A progressive, neurodegenerative disease characterized by loss of function and death of nerve cells in several areas of the brain leading to loss of cognitive function such as memory and language. "Furthermore, they mentioned the correlation between the upregulation of INPPL1 and cognitive regression in Alzheimer’s disease." (PMID 38791291, 2024).
colorectal cancer (8 papers, 2014 to 2024). A primary or metastatic malignant neoplasm that affects the colon or rectum. "This upregulation appears to be mediated on a transcriptional level, since mRNA levels of the SHIP2 encoding gene INPPL1 are also increased in colorectal carcinoma samples." (PMID 27716613, 2016). "We found that SHIP2 and INPPL1 expression is increased in colorectal cancer tissue in comparison to adjacent normal tissue, and this is correlated with decreased patient survival." (PMID 27716613, 2016). "They discovered that the transcription of INPPL1 into mRNA as well as protein expression was correlated with increased lymph node metastasis, more distant metastasis, and reduced overall survival in patients with colorectal cancer." (PMID 38791291, 2024). "We show that SHIP2 and INPPL1 expression are increased in colorectal cancer tissue in comparison to adjacent normal tissue, which results in worse patient outcome." (PMID 27716613, 2016).
metabolic syndrome (6 papers, 2013 to 2024). A cluster of metabolic risk factors for CARDIOVASCULAR DISEASES and TYPE 2 DIABETES MELLITUS. "Patients with T2D, on the other hand, had in INPPL1 SNPs that are associated with and could predispose to the metabolic syndrome, hypertension and T2D." (PMID 31342643, 2020).
Hypertension (5 papers, 2008 to 2025). The presence of chronic increased pressure in the systemic arterial system. "The human INPPL1 gene is located in the chromosome 11q13-14, region that has been suggested to be linked to T2D with insulin resistance and hypertension." (PMID 23762820, 2013).
colon cancer (4 papers, 2014 to 2022). "INPPL1 mutations have been previously reported and occur in ~4% of colon tumors." (PMID 24943349, 2014). "As knockdown of INPPL1 led to growth suppression, we hypothesize that this mutation may lead to a gain of function of INPPL1 thereby playing an oncogenic role in colon cancer as indicated by our in vitro studies." (PMID 24943349, 2014). "Thus we performed additional functional genomic and mechanistic studies using RNAi to better understand the role of INPPL1 in colon cancer cell growth and signaling." (PMID 24943349, 2014). "New insights into the role of INPPL1 in colon tumor cell growth have also been identified." (PMID 24943349, 2014). "Upon INPPL1 knockdown, we observed significant negative changes in phopho-signaling of key effectors of the PI3K/AKT pathway that suggest INPPL1 might promote growth in colon cancer." (PMID 24943349, 2014).
melanoma (4 papers, 2011 to 2024). A malignant, usually aggressive tumor composed of atypical, neoplastic melanocytes. "In contrast, the authors mention that higher expression of miR-205, which targets the INPPL1 gene encoding for SHIP2, has been associated with unknown alterations in melanocytes, which ultimately lead to their transformation into melanoma cells." (PMID 38791291, 2024). "MicroRNA targeting of INPPL1 (SHIP2) by miR-205 has recently been correlated with oncogenic transformation in melanoma." (PMID 33672717, 2021). "Our in vitro inhibition results support INPPL1 as the main responsible for melanocytic cell migration and invasion and, therefore, the miR-205-mediated suppression of melanoma progression would be due, at least in part, to the reduced expression of INPPL1." (PMID 32179834, 2020). "Among INPPL1 and BTBD3, INPPL1 was found to be the most clinically relevant gene that seems to be mediator of miR-205 suppression of melanoma progression." (PMID 32179834, 2020). "This study supports INPPL1 as a miR-205 target gene and, therefore, that the involvement of miR-205 in the metastatic dissemination of malignant melanoma is, at least in part, via INPPL1." (PMID 32179834, 2020). "Survival analysis (Kaplan-Meier curves) showed that INPPL1 was significantly associated with lymph node metastasis-free survival (LNMFS), distant metastasis-free survival (DMFS) and melanoma specific survival (MSS)." (PMID 32179834, 2020). "All three (LNMFS, DMFS and MSS) were significantly shorter in patients with primary melanomas showing INPPL1 levels above the median." (PMID 32179834, 2020). "When the time to the event is taken into consideration, our findings demonstrate an inverse correlation of INPPL1 with lymph node and distant metastasis-free survivals and a direct correlation with melanoma specific mortality." (PMID 32179834, 2020). "In summary, our results support the value of INPPL1 miR-205-regulated gene as a prognostic biomarker of human melanoma, which may be helpful when miRNA expression cannot be determined." (PMID 32179834, 2020). "Interestingly, our clinical data showed that INPPL1 was significantly associated with lymph node metastasis-free survival (LNMFS), distant metastasis-free survival (DMFS) and melanoma specific survival (MSS)." (PMID 32179834, 2020). "In this regard, not only INPPL1 but both, INPPL1 and BTBD3 expression were significantly higher in primary melanomas that developed any type of metastasis (p < 0.001 and p 0.021, respectively)." (PMID 32179834, 2020). "INPPL1 and BTBD3 were downregulated when melanoma cells expressed miR-205, indicating that these genes are potential miR-205 targets." (PMID 32179834, 2020). "Molecular mechanisms by which INPPL1 and BTBD3 affect melanoma progression require further investigation as well as their potential therapeutic value in order to block the metastatic dissemination of cutaneous malignant melanoma." (PMID 32179834, 2020). "miR-205, INPPL1, BTBD3 and ATF4 expression was measured by RT-qPCR in human primary melanoma tissue samples." (PMID 32179834, 2020). "Thus, we found INPPL1 was the only gene whose expression was significantly higher in primary melanomas which further developed distant metastasis than in non-metastatic primary melanomas (p 0.002)." (PMID 32179834, 2020). "INPPL1 and BTBD3 expression was significantly higher in ulcerated than in non-ulcerated primary melanomas (p < 0.001 in both cases)." (PMID 32179834, 2020).
cognitive decline (3 papers, 2021 to 2024). "Recent network-based approach has unraveled that SHIP2 is also linked to AD and cognitive decline: upregulation of INPPL1 transcript in the brain significantly correlates with cognitive decline in human AD patients." (PMID 33716646, 2021). "While INPPL1 has been identified as one of the most significant genes whose RNA expression correlates with cognitive decline, the potential alteration of SHIP2 expression and localization during the progression of AD remains largely unknown." (PMID 38833073, 2024).
Glucose intolerance (2 papers, 2016 to 2019). Glucose intolerance (GI) can be defined as dysglycemia that comprises both prediabetes and diabetes. "We detected eQTLs for genes known to carry functional variants contributing to glucose intolerance QTLs in the GK rat, including the inositol polyphosphate phosphatase-like 1 (Ship2 and Inppl1) and the insulin degradation enzyme (Ide)." (PMID 31213483, 2019). "Inppl1 transgenic mice show impaired insulin signaling and glucose intolerance, while Inppl1 KO mice are highly resistant to weight gain on a high-fat diet." (PMID 27834631, 2016).
keratoconus (2 papers, 2023). A degenerative, structural disorder of the eye, characterized by a cone-shaped protrusion of the cornea. "Thus, variants in INPPL1 may be associated with the development of keratoconus." (PMID 37895187, 2023). "Given the involvement of INPPL1 in the apoptosis of stromal keratocytes exposed in the proband OFT-00818, it is suggested as a possible candidate gene in the etiology of keratoconus." (PMID 37895187, 2023). "The mutant form of miR-184 fails the competition role of wild-type miR-184 with miR-205 for targeting the 3′UTRs of INPPL1 and ITGB4 and contributes to familial keratoconus with cataracts." (PMID 38174044, 2023).
lymph node metastasis (2 papers, 2014 to 2020). "More importantly, INPPL1 correlates with the development of distant and lymph node metastasis and, both, INPPL1 and BTBD3, with the development of any type of metastasis." (PMID 32179834, 2020).
lymphedema (2 papers, 2014 to 2025). Excess fluid collection in tissues, causing swelling. "We report here a nucleus family with inherited non-syndromic lymphedema with a distinct heterozygous non-synonymous rare mutation in the INPPL1 gene that encodes the SHIP2 phosphatase." (PMID 25383712, 2014). "Interestingly, individuals in this family that harbored mutations in both INPPL1 and HGF showed more severe lymphedema symptoms." (PMID 25383712, 2014).
acute myeloid leukemia (1 paper, 2025). Acute myeloid leukemia (AML) is a group of neoplasms arising from precursor cells committed to the myeloid cell-line differentiation. "We extended this analysis to another tumor cell line (the human acute myeloid leukemia cell line MOLM13) that is growth resistant with the SHP2 inhibitor SHP099 after KO of the INPPL1 or MAP4K5 genes (GSE218491, GSE21223)." (PMID 40131370, 2025).
autoimmune disease (1 paper, 2025). A disorder resulting from loss of function or tissue destruction of an organ or multiple organs, arising from humoral or cellular immune responses of the individual to their own tissue constituents. "STX8 and YES1 are implicated in T-cell activation, MAP4K5, RRM2B, FOXO1, ERBB2IP and INPPL1 can promote inflammation and KIM1, MVK and BANK1 have been associated with autoimmune diseases." (PMID 40247373, 2025).
memory impairment (1 paper, 2016). "Then, we examined the role of SHIP2 (INPPL1) in memory impairment in vivo using Inppl1 siRNA-expressing lentivirus (lenti-siInppl1)." (PMID 27834631, 2016).
cancer (33 papers, 2011 to 2025). A tumor composed of atypical neoplastic, often pleomorphic cells that invade other tissues. "While FoxM1 and C-met are related to the active proliferative ability of cells in different types of cancer, Inppl1 is associated to a bad prognosis in HCC patients." (PMID 34737944, 2021). "INPPL1 mRNA expression was significantly increased in the carcinoma group (P < 0.001)." (PMID 27716613, 2016). "For example, several genes such as DKK1/2, CSNK1A1, INPP5D, and INPPL1 in the cases we discussed in detail are not present on the cancer panels we examined, yet their functional roles in respective signaling pathways are well-documented." (PMID 27245685, 2016).
tumor (29 papers, 2011 to 2025). "The research on SHIP2 encoded within the INPPL1 gene has been focused on its potential as an oncogene or tumor suppressor." (PMID 38791291, 2024). "The INPPL1 E567G mutation discovered in tumor CLN2 resides within the catalytic inositol polyphosphate 5-phosphatase domain that is critical to inositol phosphatase activity, and is predicted to be damaging by SIFT." (PMID 24943349, 2014). "Linked to a proliferative, invasive, and metastatic phenotype in HCC, we further detected high levels of expression of factors essential for tumor progression such as FoxM1, C-met, and Inppl1 in AS-30D cells compared with normal hepatocytes." (PMID 34737944, 2021). "Additionally, we investigated the association of INPPL1, BTBD3 and ATF4 expression with histological tumor parameters such as Breslow thickness and ulceration as well as with patient gender and age at diagnosis." (PMID 32179834, 2020). "INPPL1 has been shown to act as either a tumor suppressor or an oncogene in different tumor types." (PMID 24943349, 2014). "Here, we found that the downregulation of Inppl1 promoted PI3K signaling and enhanced cell proliferation, and that Inppl1 represents a new tumor suppressor gene in ICC." (PMID 38212325, 2024). "Irregular expression of INPPL1 may then disrupt the normal PI3K/Akt pathway, which has an important function in controlling cell proliferation and cell death as well as tumor development and progression." (PMID 33546420, 2021).
skeletal dysplasia (3 papers, 2015 to 2025). Any Mendelian diseases that affects growth and development of the skeleton. "Four variants were highlighted in four genes known to cause skeletal dysplasias, namely EBP, INPPL1, COL1A2, and SLC26A2, being the last two characterised by high in utero lethality." (PMID 41153384, 2025).
INPPL1 also shares sentences with these, for which no sentence is quoted: Insulin resistance (13 papers); gastric cancer (9); glioblastoma (8); hepatocellular carcinoma (8); atherosclerosis (4); diabetic kidney disease (4); infection (3); kidney disease (3); liver cancer (3); metabolic disorders (3); glioma (2); laryngeal squamous cell carcinoma (2); lung carcinoma (2); neurodegenerative disease (2); non-small cell lung carcinoma (2); squamous carcinoma (2); acute lung injury (1); amyloid (1); Atrophy (1); breast tumours (1); cardiovascular disease (1); cataract (1); cervical cancer (1); cognitive deficits (1); colorectal adenoma (1); cutaneous malignant melanoma (1); depression (1); diffuse Lewy body disease (1); dysplasia (1); epilepsy (1).
A further 17 diseases each share a sentence with INPPL1 in 1 paper.